ABCG2 (ATP binding cassette subfamily G member 2 (JR blood group))
Diseases named in the same sentence as ABCG2 in open-access papers (continued):
Sharing a sentence is not in itself a finding about the gene and the disease.
Skin rash (7 papers, 2015 to 2025). A red eruption of the skin. "While the results did not reinforce the association between hepatotoxicity and genetic polymorphisms, they suggested that ABCG2 34G > A was a useful predictor of skin rash of grade 2 or higher level." (PMID 30326853, 2018). "Altogether, this systematic review indicates that genetic variants of ABCB1 (rs1045642 and rs1128503) and ABCG2 (rs2231142) transporters are likely to exhibit clinical implications relating to the presence of adverse reactions (skin rash and diarrhea) to gefitinib in patients with NSCLC." (PMID 38790220, 2024).
brain cancer (6 papers, 2011 to 2025). A primary or metastatic malignant neoplasm affecting the brain. "GBM also remains one of the most treatment-resistant forms of brain cancer, largely due to the overexpression of ATP-binding cassette transporters such as ABCG2." (PMID 41323785, 2025).
chorioamnionitis (6 papers, 2016 to 2021). A morphologic finding indicating inflammation of the fetal sac membranes. "Conversely, BCRP/ABCG2 levels were found elevated in human preterm placental fragments from patients with chorioamnionitis." (PMID 32916274, 2020). "In sharp contrast, the placenta from preterm pregnancies complicated by chorioamnionitis exhibited increased ABCG2 and BCRP expression." (PMID 31561453, 2019). "Up-regulation of ABCB9, ABCC2 and ABCF2 mRNA was detected in chorioamnionitis (p<0.05), whereas placental ABCB1 (P-gp; p=0.051) and ABCG2 (breast cancer resistance protein-BCRP) mRNA levels (p=0.055) approached near significant up-regulation." (PMID 29402780, 2018). "Similarly, there was a significant correlation between the severity of chorioamnionitis and the increased expression of ABCB1, ABCC2, ABCF2 and ABCG2." (PMID 29402780, 2018).
clear cell renal cell carcinoma (6 papers, 2017 to 2025). "Some reports have also suggested that expression levels of another ABC transporter, ABCG2 (encoded by the ABCG2 gene), also expressed in kidney cancers, can predict overall survival in patients with clear cell renal carcinoma." (PMID 37840856, 2023). "One exception was renal clear cell carcinoma, where significant overexpression of ABCG2 was confirmed in both datasets." (PMID 37445716, 2023). "The regulation of ABCG2 expression by miR-212-3p was also observed in clear cell renal cell carcinoma." (PMID 35628654, 2022). "miRNAs (miR-132-3p, miR-212-3p) have been found to be involved in post-transcriptional regulation of ABCG2 in clear cell renal cell carcinoma." (PMID 33066132, 2020). "We aimed to evaluate the prognostic significance of ABCG2 expression in patients with clear cell renal cell carcinoma." (PMID 28347288, 2017). "The current data suggests that ABCG2 may serve as a prognostic marker for overall survival in patients with clear cell renal cell carcinoma." (PMID 28347288, 2017).
coronary artery disease (6 papers, 2015 to 2024). "In the investigation of three white subjects, ATP binding cassette subfamily G member 2 encoded by ABCG2 is associated with severe coronary artery disease under the influence of single-nucleotide polymorphisms." (PMID 34012683, 2021). "The use of ABCG2 inhibitors in cancer patients therefore might cause drug-induced cardiotoxicity, particularly in hypoxemic patients or ischemic heart disease." (PMID 28270772, 2017).
esophageal squamous cell carcinoma (6 papers, 2012 to 2021). Esophageal squamous cell carcinoma (ESCC) is a type of esophageal carcinoma (EC) that can affect any part of the esophagus, but is usually located in the upper or middle third. "Meanwhile, higher ABCG2 mRNA expression also represented an unfavorable prognostic factor of esophageal squamous cell carcinoma." (PMID 33050883, 2020).
Insulin resistance (6 papers, 2024 to 2025). Increased resistance towards insulin, that is, diminished effectiveness of insulin in reducing blood glucose levels. "Therefore, URAT1, GLUT9, and ABCG2 can be therapeutic targets for uricosuric drugs in patients with insulin resistance and hyperinsulinemia." (PMID 38474414, 2024). "For instance, insulin resistance enhances renal reabsorption of uric acid by increasing the activity of transporters, such as GLUT9 and URAT1, while simultaneously inhibiting ABCG2‐mediated uric acid excretion." (PMID 39901609, 2025). "Insulin resistance and hyperinsulinemia increase UA transport by URAT1 and GLUT9 and decrease UA transport by ABCG2, which may induce a decrease in renal UA clearance." (PMID 38474414, 2024).
malaria (6 papers, 2013 to 2025). Malaria is a serious and sometimes fatal disease caused by a parasite that commonly infects a certain type of mosquito which feeds on humans. "Interestingly, the ATP2B4 minor haplotype, protecting against malaria, correlated with an increased disease susceptibility, while in diabetic patients disease susceptibility was lower in the presence of a reduced-function ABCG2 transporter variant." (PMID 39752416, 2025).
metastatic tumors (6 papers, 2012 to 2025). "ABCG2 was more frequently expressed (58%) in cancer tissue compared to other lesions, and its expression correlated with low differentiation, metastatic disease, and poor prognosis." (PMID 40548120, 2025). "For instance, resistance of metastatic tumors to the anthracycline doxorubicin (DOX) has been linked to overexpression of ABC transporters ABCB1 (MDR1/P-glycoprotein), ABCC1 (MRP1), ABCC2 (MRP2) and ABCG2 (MXR, BRCP)." (PMID 22791660, 2012). "Moreover, a change in ABCG2 expression may occur during the progression of CRC (from primary to metastatic disease, which might be related to the systemic treatment applied)." (PMID 28880238, 2017). "Furthermore, in line with the ABCG2 expression level, TOX3 showed a high expression in the recurrent or metastatic tumor tissues of patients with CRC." (PMID 37708089, 2023).
psoriasis (6 papers, 2013 to 2024). An autoimmune condition characterized by red, well-delineated plaques with silvery scales that are usually on the extensor surfaces and scalp. "Our data revealed an influence of ABCG2 gene variations on the predisposition to psoriasis; however, there are several limitations in this study." (PMID 34680995, 2021). "The genotype distribution of two ABCG2 single nucleotide polymorphisms (SNPs), rs2231142 and rs2231137, was examined in 410 psoriasis patients and 1,089 gender-matched non-psoriasis controls." (PMID 34680995, 2021). "In this study, we aimed to evaluate the role of ABCG2 gene polymorphisms on the susceptibility to psoriasis." (PMID 34680995, 2021). "In conclusion, the present study revealed the novel finding that ABCG2 rs2231142 polymorphism was associated with psoriasis, indicating a link of altered ABCG2 expression or function to psoriasis pathogenesis." (PMID 34680995, 2021). "Since a genetic predisposition to psoriasis was noted, we further analyzed the effect of ABCG2 gene polymorphisms on clinical characteristics in patients with psoriasis." (PMID 34680995, 2021). "The present study, for the first time, investigated the role of ABCG2 polymorphism as a possible genetic risk factor for psoriasis." (PMID 34680995, 2021). "The link between psoriasis and ABCG2 gene polymorphisms implies that the polymorphic alleles may possess a protective effect from developing this cutaneous disease." (PMID 34680995, 2021). "Our results indicated that the ABCG2 gene polymorphism was associated with the risk of psoriasis." (PMID 34680995, 2021). "Therefore, the aim of this study was to test the hypothesis that ABCG2 genetic polymorphism may potentially confer the susceptibility to psoriasis." (PMID 34680995, 2021). "Through assessing the genotype distribution of two ABCG2 single nucleotide polymorphisms (SNPs), rs2231142 and rs2231137, in 410 psoriatic patients and 1089 controls, we demonstrated that ABCG2 gene polymorphism was associated with the predisposition to psoriasis." (PMID 34680995, 2021). "We found significant differences in genotype frequencies of ABCG2 rs2231142 between the psoriasis group and control population." (PMID 34680995, 2021). "Increased expression of ABCG2 in peripheral blood mononuclear cells was described in psoriasis as well." (PMID 34680995, 2021). "The role of ABCG2 in inflammatory diseases has been described in rheumatoid arthritis and psoriasis." (PMID 34680995, 2021). "Additionally, more functional experiments are needed to determine the role of ABCG2 in the pathogenesis of psoriasis." (PMID 34680995, 2021). "A recent study found that CD147 promotes MTX resistance of immune cells through ABCG2 in psoriasis." (PMID 30374344, 2018).
acute leukemia (5 papers, 2012 to 2023). A clonal (malignant) hematopoietic disorder with an acute onset, affecting the bone marrow and the peripheral blood. "In adult acute leukemia, ABCG2 expression can be elevated by the inactivation of phosphatase and tensin homolog (PTEN) protein, achieved in this study by reversing the PI3K/Akt pathway inhibition." (PMID 28903328, 2017).
cholangiocarcinoma (5 papers, 2022 to 2026). A carcinoma that arises from the intrahepatic biliary tree (intrahepatic cholangiocarcinoma) or from the junction, or adjacent to the junction, of the right and left hepatic ducts (hilar cholangiocarcinoma). "Single-cell transcriptomics revealed elevated ABCG2 expression in cholangiocarcinoma endothelial cells, while immune infiltration analysis showed significant associations between ABCG2 expression and both endothelial cell and macrophage infiltration." (PMID 40282409, 2025). "GHCer-induced GR and ABCG2 upregulation were assessed in GBC cell lines, patient-derived xenograft (PDX), and a thioacetamide (TAA)-induced rat cholangiocarcinoma model." (PMID 41799195, 2026). "AIB1 is overexpressed in CCA, and AIB1-induced ABCG2 overexpression plays a vital role in promoting drug efflux, contributing to enhanced chemoresistance in human cholangiocarcinoma." (PMID 35372014, 2022).
cholestasis (5 papers, 2013 to 2022). Impairment of the bile flow caused by obstruction within the liver, or outside the liver in the bile duct system. "Recent studies have reported that Abcg5 deficient mice were more susceptible to cholestasis compared to normal, and that ABCG2 serves as a bile acid and cholesterol transporter." (PMID 25798860, 2015). "Thus, the down-regulation of ABCG2 and ABCG8 may involve in the disruption of bile acid and cholesterol homeostasis during cholestasis." (PMID 25798860, 2015).
colorectal adenocarcinoma (5 papers, 2011 to 2025). The most common type of colorectal carcinoma. "Another study reported a decrease in the uptake of PhA photosensitizer in HT-29 human colorectal adenocarcinoma cells overexpressing ABCG2 both in vivo and in vitro." (PMID 39403604, 2024).
colorectal tumor (5 papers, 2016 to 2023). "In 7 of 12 datasets collected in Oncomine, 17 out of 34 analyses found ABCG2 to be among 10% of the top underexpressed genes in colorectal tumours." (PMID 37445716, 2023). "Hence, it appears that in the ABCG2 gene, some sites other than the promoter can influence its expression, and that this phenomenon can be restricted to certain localizations of the colorectal tumour." (PMID 37445716, 2023). "The decrease in ABGC2 expression level observed in primary colorectal tumours raises the question of whether ABCG2 is also underexpressed in metastatic tissue." (PMID 37445716, 2023). "Several studies mentioned the expression level of membranous ABCG2 in colorectal tumors, and suggested that it could be used to predict post-operative patient's survival as prognostic biomarker." (PMID 31516883, 2018). "Consistently, the expressions of genes related to cancer stem-like traits were increased in the colorectal tumors of OXA treatment mice, compared to NS treatment mice, including TOX3, WDR5, and ABCG2." (PMID 37708089, 2023).
Hypercholesterolemia (5 papers, 2019 to 2022). An increased concentration of cholesterol in the blood. "A relevant fact is that mRNA expression levels ofABCG2 appear to be higher in individuals with hypercholesterolemia (Rodrigueset al., 2009); likewise, the activity of ABCG2 has been associated with cholesterol levels bothin vitro andin vivo (Toet al., 2014)." (PMID 34631016, 2021).
inflammatory bowel disease (5 papers, 2015 to 2023). A spectrum of small and large bowel inflammatory diseases of unknown etiology. "Further, the ABCG2 protein is seen to be downregulated in colon biopsies from patients with active inflammatory bowel disease." (PMID 31739430, 2019).
intrahepatic cholestasis (5 papers, 2013 to 2023). A cholestasis characterized by impairment of the bile flow caused by obstruction located in the liver. "The reduced expression of the canalicular transporters ABCC2, ABCG2 and of the cholesterol transporter ABCG5 leads to impaired bile acid, bilirubin and cholesterol excretion and in the long term to intrahepatic cholestasis as was observed in DILI patients treated with diclofenac." (PMID 29296203, 2017).
metastatic colorectal cancer (5 papers, 2014 to 2023). "In this study we investigated the use of cancer cell protein expression of ABCG2 to predict efficacy of systemic first-line irinotecan containing therapy in patients with metastatic colorectal cancer (mCRC)." (PMID 32708825, 2020). "Combination of SNPs with MTHFR and ABCG2 may play a role in helping clinicians to select first-line chemotherapy for patients with metastatic colorectal cancer." (PMID 24338217, 2014). "Monoclonal antibodies against EGFR are commonly used in the treatment of metastatic colorectal cancer, and some of these agents synergistically inhibit both EGFR phosphorylation and ABCG2 drug efflux activity." (PMID 37445716, 2023). "A total of 132 metastatic colorectal cancer patients were genotyped for CYP3A4*1B, CYP3A4*18, CYP3A5*3, DPYD*2A, DPYD*5, DPYD c.1774C > T, UGT1A1*28, UGT1A1*6, ABCB1 c.1236C > T, ABCB1 c.3435C > T, ABCC2 c.3972C > T, and ABCG2 c.421C > A." (PMID 32778670, 2020).
oral squamous cell carcinoma (5 papers, 2011 to 2023). "In this study, we analyzed immunoreactive protein and relative gene expression of ABCG2 and Bmi-1 in a panel of eight cell lines derived from oral tissues with a spectrum of diseases ranging from normal through mild and moderate/severe dysplasia to oral squamous cell carcinoma (OSCC)." (PMID 24415717, 2014). "Expression of ABCG2 and Bmi-1 was rigorously evaluated in a collection of eight oral cell lines originating from normal tissue (OKF6-TERT2), mild dysplasia (DOK), severe dysplasia (POE-9n), and oral squamous cell carcinoma (PE/CA PJ15, SCC04, SCC25, SCC09, and SCC15)." (PMID 24415717, 2014).
rheumatoid arthritis (5 papers, 2016 to 2025). A chronic, systemic autoimmune disorder characterized by inflammation in the synovial membranes and articular surfaces. "The phenomenon that functionality of ABCG2 was correlated with the disease activity in patients with recently diagnosed rheumatoid arthritis could be due to an inherent feature of lymphocytes." (PMID 34680995, 2021). "Summing up, our results demonstrate that patients with active rheumatoid arthritis have an increased function of ABCB1 and ABCG2, and that disease activity is the variable with the strongest association with this phenomena, even though there is also an association with treatment duration." (PMID 27442114, 2016).
acute promyelocytic leukemia (4 papers, 2016 to 2025). An aggressive form of acute myeloid leukemia (AML), characterized by arrest of leukocyte differentiation at the promyelocyte stage, due to a specific chromosomal translocation t(15;17) in myeloid cells. "In the promyelocytic leukemia HL-60, the promoters of ABCB1 and ABCG2 were highly methylated." (PMID 27689338, 2016).
adenoma (4 papers, 2015 to 2023). A neoplasm arising from the epithelium. "ABCG2 mRNA levels were statistically significantly lower in all adenoma tissues compared to mRNA levels in unaffected tissue from the same individuals and compared to mRNA levels in tissue from healthy individuals (all p<0.0001)." (PMID 25793771, 2015). "In the present study our aim was to assess the roles of ABCC2 and ABCG2 in the normal-adenoma-carcinoma sequence and we therefore measured ABCC2 and ABCG2 mRNA levels in intestinal tissues from patients with colorectal adenomas and CRC." (PMID 25793771, 2015). "The authors found low levels of ABCG2 protein and ABCG2 mRNA in the adenoma tissue using adjacent tissue as control." (PMID 25793771, 2015). "In conclusion, this study found that ABCC2 and ABCG2 gene expression levels were altered in mild/moderate dysplasia in the normal-adenoma-carcinoma sequence suggesting that these ABC transporters are involved in early carcinogenesis similar to ABCB1." (PMID 25793771, 2015). "Furthermore, we found significantly lower level of ABCG2 in adenomas and carcinomas compared to the level in unaffected tissue from the same individuals and as compared to tissue from healthy individuals." (PMID 25793771, 2015). "Furthermore, ABCG2 mRNA levels were significantly lower in adenomas and carcinomas compared to the level in unaffected tissue from the same individuals and compared to tissue from healthy individuals (P<0.0001 for all)." (PMID 25793771, 2015). "The finding of lowered ABCG2 level in adenomas with mild/moderate dysplasia suggests that low ABCG2 activity may hamper export of food carcinogens in adenomas with mild/moderate dysplasia." (PMID 25793771, 2015). "Moreover, in an animal model, down-regulation of ABCG2 protein expression was found in adenoma tissue compared to adjacent normal tissue." (PMID 25793771, 2015). "ABCG2 mRNA levels were significantly lower in adenomas and carcinomas compared to unaffected tissue from the same individuals and to tissue from healthy; however, the adjacent normal tissue of cancer patients demonstrated higher ABCG2 expression than the tissue from healthy individuals." (PMID 37445716, 2023). "Downregulation of ABCG2/Abcg2 was found to impair the barrier function of the intestine, thus leading to higher carcinogen concentrations in colorectal adenomas in mice and humans and promoting the adenoma–carcinoma sequence via DNA-bound accumulation of carcinogenic xenobiotics." (PMID 37445716, 2023). "ABCC2 and ABCG2 mRNA levels were assessed in intestinal tissue from 122 CRC cases, 106 adenoma cases (12 with severe dysplasia, 94 with mild-moderate dysplasia) and from 18 controls with normal endoscopy." (PMID 25793771, 2015). "Our study is also in agreement with a study of ABCG2 and ABCC2 protein and ABCG2 mRNA levels in 29 adenomas from 21 patients." (PMID 25793771, 2015).
B cell lymphoma (4 papers, 2015 to 2023). "Acquired DR could be associated with increased ABCB1 expression in B-cell lymphomas, while in T-cell lymphomas an increase in ABCG2 expression was found." (PMID 29061939, 2015). "Such epigenetic markers promote GLI-1 occupation of ABCG2 gene promoter sequences and induce the expression of ABCG2, which is involved in chemoresistance in the presence of doxorubicin and methotrexate in non-solid tumors and B-cell non-Hodgkin lymphoma cells." (PMID 28978016, 2017).
COVID-19 (4 papers, 2023 to 2025). A disease caused by infection with severe acute respiratory syndrome coronavirus 2. "In contrast, diabetic patients carrying the minor variant of ABCG2, are probably less likely to have hospitalization-requiring COVID-19." (PMID 39752416, 2025). "In contrast, we observed that type 2 diabetic patients carrying the minor variant of ABCG2, are probably less likely to have hospitalization-requiring COVID-19, although these results were not statistically significant." (PMID 39752416, 2025). "This was reflected by increased expression over time of genes involved in heme metabolism (such as ABCG2 and GATA1) until they were no longer significantly differentially expressed compared to non-COVID-19 sepsis patients by D7." (PMID 37090709, 2023).